DRD2 (dopamine receptor D2)
Diseases named in the same sentence as DRD2 in open-access papers (continued):
Sharing a sentence is not in itself a finding about the gene and the disease.
schizophrenia (continued). "We sequenced 2,111‐bp fragment of DRD2 gene promoter region in 306 schizophrenic patients and 324 healthy controls to find association between DRD2 and schizophrenia." (PMID 30657260, 2019). "But we cannot definitively exclude the possible association between DRD2 gene promoter region and schizophrenia risk." (PMID 30657260, 2019). "Several genes, including DRD2, have been associated with schizophrenia by GWAS, even though, most findings have implicated different variants from those detected by candidate gene approaches." (PMID 30687136, 2018). "In this paper we designed a data-driven method based on complex network analyses and successfully detected a pivotal community for DRD2, a relevant gene linked to Schizophrenia." (PMID 29304112, 2018). "The DRD2 locus is the only dopamine receptor gene for which common variants have been associated to schizophrenia risk by GWAS." (PMID 30687136, 2018). "A prototypical example is provided by rs2514218, a SNP in DRD2 gene that was associated with schizophrenia in a large GWAS published by the Psychiatric Genomics Consortium." (PMID 30687136, 2018). "Other schizophrenia risk loci with TCF4 binding sites include DRD2, TSNARE1, and GRIA1, all of which are down-regulated in TCF4-depleted cells and MIR137/DPYD." (PMID 29228394, 2018). "For instance, dopamine D2 receptor (DRD2) played an essential role in dopamine signaling which was strongly implicated in the etiology of schizophrenia (SZ), and was also one of the targets of Dopamine." (PMID 29212201, 2017). "In our study, the DRD2 gene is involved in attention while the COMT gene is implicated in executive functions in patients with schizophrenia." (PMID 28085950, 2017). "The phosphoinositide-3 kinase - protein kinase B (PI3K-Akt) pathway is an important downstream intracellular pathway of DRD2, which is associated with the function and development of central nervous system and the pathophysiology of schizophrenia." (PMID 29156812, 2017). "In many studies of the genetic causes of schizophrenia, Drd2 and several elements of glutamatergic transmission have been strongly implicated." (PMID 28535798, 2017). "Recent reports reinforce the importance of dopamine in schizophrenia, including strong associations with DRD2 (a target of many antipsychotic drugs)." (PMID 29181591, 2017). "Association between genetic variants of DRD2 genes and 6 cognitive scores (mean, SD) in 52 schizophrenia patients." (PMID 28085950, 2017). "DRD2 mRNA levels of all splice variants were reduced in the substantia nigra in schizophrenia compared with controls; DRD2S mRNA by 38% (F=3.05, df=55, P=0.018), DRD2L mRNA by 29% (F=3.98, df=56, P=0.051) and DRD2Longer mRNA by 22% (F=3.49, df=56, P=0.067)." (PMID 28094812, 2017). "We have previously reported a strong association between schizophrenia and various polymorphisms within the DRD2/ANKK1 locus, including rs1800497 in the ANKK1 gene, including rs2242592 in the intergenic region and rs6277 in DRD2 gene." (PMID 28085950, 2017). "They deduced that DRD2 disrupts rs1076560 (T allele) as a potential risk factor for schizophrenia in multiple subpopulations of Han Chinese." (PMID 28798405, 2017). "The aim of this study was to perform a systematic review and meta-analysis to explore the relation between three polymorphisms of the DRD2 gene (C957T, TaqI and Ser311Cys) and schizophrenia." (PMID 27829443, 2016). "To assess the relationship between the DRD2 genetic variants and the risk to develop schizophrenia, we conducted a meta-analysis of three DRD2 polymorphisms: TaqI, C957T and Ser311Cys." (PMID 27829443, 2016). "A meta-analysis showed that the Ser311Cys polymorphism (rs1801028) in DRD2 is a risk factor for schizophrenia." (PMID 26290802, 2015). "Associations of the DRD2 polymorphisms with increased risks of schizophrenia, but other than the A1-allele such as C957T (rs6277), C939T (rs6275), and missense Cys311Ser (rs1801028) variants, have also been reported." (PMID 26136653, 2015).
schizophrenia (continued). "Nevertheless, DRD2 is one of the genes that was confirmed as being associated with schizophrenia by the Working Group." (PMID 26290802, 2015). "The Dopamine D2 receptor (DRD2) is a target for antipsychotic drugs in the treatment of schizophrenia and genetic variation within and adjacent to DRD2 has been associated with schizophrenia, including in a recent large genome-wide association study." (PMID 26114663, 2015). "The genetic interaction for mitochondria function and schizophrenia were illustrated by DRD2 linked to NDUFS7 through protein-protein interactions of FLNA and ARRB2." (PMID 25522158, 2014). "Among dopamine receptors, the D2 receptor (DRD2) is implicated in the pathophysiology of multiple major psychiatric disorders including schizophrenia and drug addiction, such that many antipsychotic drugs at least partially target DRD2." (PMID 24391960, 2013). "Recent findings from Ahmadiantehrani and Ron seem to corroborate these results by revealing that upregulated DRD2 signaling, a hallmark of schizophrenia, resulted in elevated GDNF expression levels." (PMID 24324616, 2013). "The study further found that schizophrenia patients carrying risk alleles of Akt1 and DRD2 genes which influence D2 receptor function had less illness-related reductions in IQ levels with higher doses of antipsychotics than non-risk allele carriers." (PMID 23449679, 2012). "Several studies and meta-analyses point to potential involvement of DRD2 in susceptibility to schizophrenia." (PMID 20179754, 2010). "While the specific genes conferring risk for schizophrenia are still undetermined, several studies and meta-analyses point to the potential involvement of the gene for dopamine D2 receptors (DRD2)." (PMID 20179754, 2010). "Variation of the gene coding for D2 receptors (DRD2) has been associated with risk for schizophrenia and with working memory deficits." (PMID 20179754, 2010). "We examined the role of Taq1B, Taq1D, S311C, H313H and Taq1A polymorphisms of DRD2 gene in schizophrenia and antipsychotic treatment response in 213 patients and 196 controls from a homogenous South Indian population." (PMID 17651483, 2007). "In the past, several studies have been carried out to identify the role of DRD2 polymorphism representing variable receptor densities in schizophrenia." (PMID 17651483, 2007). "But not much of information is available on therapeutic response of antipsychotics in relation to DRD2 variants in schizophrenia." (PMID 17651483, 2007). "To date, the issue remains underreported, as is exemplified by studies of a diallelic DRD2 missense variant in schizophrenia." (PMID 18154681, 2007). "Several studies have shown positive association of D2 subtype of dopamine receptor (DRD2) in schizophrenia however, this was refuted by many others." (PMID 17651483, 2007). "Meta-analyses of case control studies with DRD2 S311C provides strong evidence that Cys311 allele of DRD2 influences susceptibility to schizophrenia and that the risk associated with this polymorphism is actually greater than either HTR2A or DRD3." (PMID 17651483, 2007). "This is probably the first study which tries to dissect the role of DRD2 polymorphisms in schizophrenia to the level of symptoms." (PMID 17651483, 2007). "Moreover, ANO1 cKO mice exhibited elevated Drd2 expression in the ventral medial geniculate nucleus (MGv) and transcriptomic alterations overlapping with schizophrenia-associated genes." (PMID 41527097, 2026). "Epigenetic changes have been well-established in BDNF, COMT, FKBP5, NR3C1, SLC6A4, and DRD2, genes associated with psychiatric disorders, including schizophrenia, major depressive disorder (MDD), bipolar disorder (BP), post-traumatic stress disorder (PTSD), and autism spectrum disorder (ASD)." (PMID 41234420, 2025).
schizophrenia (continued). "In terms of neural apoptosis, HERV-W env triggers aberrant dopaminergic neuronal processes via DRD2/PP2A/AKT1/GSK3 for schizophrenia risk and promotes antiviral immune response in schizophrenia through the linc01930/cGAS/STING pathway, resulting in neuronal apoptosis." (PMID 40128823, 2025). "As such, it may appear that variations in the DRD2 gene may confer a risk factor for developing schizophrenia, as well as having a modifier effect." (PMID 39595853, 2024). "The Drd2 gene, encoding the dopamine D2 receptor (D2R), was recently indicated as a potential target in the etiology of lowered sociability (i.e., social withdrawal), a symptom of several neuropsychiatric disorders such as Schizophrenia and Major Depression." (PMID 38114631, 2024). "A SNP residing in the coding region of ANKK1 (rs1800497, commonly known as TaqIA SNP) has been previously associated with alcoholism, schizophrenia and eating disorders, although it is unclear whether this SNP exerts its effect via DRD2 or ANKK146." (PMID 37117178, 2023). "Some studies have suggested that the rs1800497 polymorphism is always accompanied by an abnormal expression of the DRD2 gene in the brain tissue and is associated with several psychiatric disorders, such as anxiety, depression, schizophrenia, bipolar disorder, and autism spectrum disorder." (PMID 37274216, 2023). "Moreover, the gene coding for D2R (DRD2) has been associated with schizophrenia at a genome-wide level." (PMID 35871219, 2022). "However, we identified a link between the functional polymorphism DRD2 (rs1799732) and the development of MetS in women with schizophrenia taking long-term antipsychotics." (PMID 35893053, 2022). "We conducted the current study to determine from two polymorphisms of the DRD2 gene (rs1799732, rs4436578) whether there is an association with the prevalence of metabolic syndrome in our population of 517 patients with schizophrenia." (PMID 35893053, 2022). "More specifically, these SNPs were associated with reduced DRD2 expression in prefrontal cortex and striatum as well as with altered activity of the striato-thalamic-prefrontal pathway in healthy subjects and in schizophrenia." (PMID 33917417, 2021). "The study recruited 36,989 patients with schizophrenia and 113,075 controls and revealed 108 genetic loci associated with the pathology of schizophrenia, including DRD2 and several genes related to neuronal transmission, which supports the conventional pathological theory of schizophrenia." (PMID 34063598, 2021). "The results suggest that rs6276 in DRD2 may be associated with the deficit syndrome in patients with hereditary susceptibility to schizophrenia." (PMID 32565876, 2020). "The results of several studies indicate that GATAD2A may be one of the causal genes in the pathogenesis of schizophrenia, potentially through dopamine receptor D2 and nerve growth factor (NGF) pathways." (PMID 32934226, 2020). "However, to fully explore the association of DRD2 gene and schizophrenia, more and more studies are required for better understanding." (PMID 30657260, 2019). "In the current study, we try to explore whether the polymorphisms in the promoter region of DRD2 gene was involved in schizophrenia among the northern Chinese Han population." (PMID 30657260, 2019). "In fact, DRD2 has been associated with schizophrenia in a recent genome-wide association study." (PMID 29634738, 2018). "Our meta-analysis suggests an association of the DRD2 gene and the risk for schizophrenia, given that TaqI and C957T polymorphisms presented a protective effect against schizophrenia, and in the sub-analyses the C957T variant increased the risk for this disorder in the Chinese population." (PMID 27829443, 2016). "The clinical implications for the role for the DRD2 SNP rs6277 has been associated to learning, reward sensitivity, substance abuse, nicotine modulation of working memory, pharmacological interventions as well as in schizophrenia." (PMID 26307064, 2015).
schizophrenia (continued). "Genetic risk for schizophrenia has been widely investigated in a number of association studies, but there is still little evidence confirming the association of the dopamine D2 receptor (DRD2) gene with the disease." (PMID 25071490, 2014). "The genetic interaction between mitochondria function and schizophrenia may be revealed by DRD2 linked to NDUFS7 through protein-protein interactions of FLNA and ARRB2." (PMID 25522158, 2014). "Indeed, genetic variation in a number of genes involved in dopamine regulation have been linked to schizophrenia risk, including DRD2, VMAT2 (psychotic disorder) and COMT." (PMID 24618531, 2014). "We investigated whether schizotypy is related to genetic variation within the DRD2 gene and whether they interact on a series of phenotypes implicated in schizophrenia." (PMID 25071490, 2014). "Different variants of the DRD2 gene may be associated with higher perseverative responses in female schizophrenia patients, while VNTR variants of the DRD4 gene may predict for differences in age of onset in female patients." (PMID 24639636, 2014). "Various genetic studies, from classical single nucleotide polymorphism to genome-wide association studies, consistently demonstrate associations of the dopamine receptor D2 (DRD2) gene with leading pathophysiological hypotheses of schizophrenia [Schizophrenia Working Group]." (PMID 41303622, 2025). "Adult patients with schizophrenia will be randomized (2: 1) to receive PGx-assisted treatment (drug and regimen selection depending on the results of single-nucleotide polymorphisms in genes DRD2, HTR1A, HTR2C, ABCB1, CYP2D6, CYP3A5, and CYP1A2) or the standard of care." (PMID 38598465, 2024). "Moreover, selective DRD2 deletion from Nkx6.2 expressing progenitors in mice caused cognitive and negative phenotypes but not hyperlocomotion, reminiscent of the positive symptoms of schizophrenia or bipolar disorder." (PMID 37945756, 2023). "Some associations at DRD2 and several genes involved in glutamatergic neurotransmission were consistent with previous leading pathophysiological hypotheses and highlight molecules with known and potential therapeutic relevance to schizophrenia." (PMID 35990059, 2022). "Given that Drd2 is genetically linked to schizophrenia and is the target of antipsychotics, our findings may provide insight into the pathophysiological mechanisms of schizophrenia." (PMID 34750364, 2021). "More than 200 polymorphisms have been identified in DRD2, mostly in the introns and in downstream flanking region, which have been associated with addictions (alcohol, cocaine, nicotine and opioid), mood disorders, schizophrenia, movement disorders and drug response." (PMID 33917417, 2021). "A meta-analysis study on the relationships between the −141C Ins/Del (rs1799732) polymorphism in DRD2 and the risk of many neuropsychiatric disorders showed that Asian Del allele carriers had decreased chances of developing many neuropsychiatric disorders, such as schizophrenia." (PMID 33167416, 2020). "Schizophrenia GWAS studies have since identified 108 highly associated loci, and have provided some support for the utility of commonly used antipsychotic medications by highlighting variants at dopamine receptor genes, such as DRD2, to be associated with schizophrenia." (PMID 30761022, 2019). "Candidate gene studies on functional polymorphisms of DRD2 gene, involving SNPs that affect DRD2 gene expression and/or DRD2 Long/Short transcription isoform ratio, along with DRD2 membrane density, have also pointed to a role of such genetic variation in schizophrenia." (PMID 30687136, 2018). "Thus, the highest PF score of DRD2 strongly suggests the genes prioritized by Prix Fixe may represent promising causal genes for schizophrenia." (PMID 29540662, 2018).
schizophrenia (continued). "For example, DRD2 and AKT1 polymorphisms in healthy subjects – implicated in DRD2 signalling – have a selective effect on directed prefrontal-striatal connectivity, while the same polymorphisms alter the dose-response effects of anti-psychotic drugs on cognition in schizophrenia." (PMID 27450778, 2016). "Given that dysregulations in dopamine signaling are fundamental to schizophrenia, the ability of miR-9-5p to modulate DRD2 expression is particularly significant." (PMID 40779062, 2026). "We prioritized 101 schizophrenia genes, including 15 that are targeted by approved or investigational drugs (e.g., DRD2, GRIN2A, CACNA1C, GABBR2)." (PMID 41639063, 2026). "Postmortem studies show altered DRD2 methylation in the prefrontal cortex and striatum of individuals with schizophrenia." (PMID 41234420, 2025). "DRD2 GWAS signals drove enrichment for all schizophrenia treatments; a post hoc analysis excluding therapeutics that were only enriched due to DRD2 GWAS signals still revealed significant enrichment for SCZ treatments (OR = 19.49; p = 2.47e−4)." (PMID 40379965, 2025). "For instance, maternal immune activation (MIA), which is a developmental animal model for schizophrenia, leads to reduced DRD2 mRNA in adolescent offspring, which is accompanied by increased a right-side turning preference." (PMID 40002502, 2025). "Loxapine succinate is the succinate salt form of loxapine, a DRD2 antagonist used clinically for the treatment of schizophrenia." (PMID 38478584, 2024). "As already mentioned in the introductory part, DRD2 is of special importance with regard to the pathogenesis of schizophrenia." (PMID 39448630, 2024). "Specific attention is given to the impact of SNPs in DICER, DROSHA, and DGCR8, as well as the potential for changes in DRD2 gene expression driven by miR-9 and miR-326, heightening the likelihood of Schizophrenia development." (PMID 38343691, 2024). "Targeting DRD2 influences motor control, reward processing, and decision-making in conditions like Parkinson’s disease and schizophrenia." (PMID 38924082, 2024). "OLZ treatment in rats affected the 5mC levels of several genes associated with schizophrenia, including dopamine D1 receptor (DRD1), dopamine D2 receptor (DRD2), dopamine D5 receptor (DRD5), and others." (PMID 38203806, 2024). "Rs2514218 located near the DRD2 gene is the only locus related to dopamine signaling that has been found by the Schizophrenia Psychiatric GWAS Consortium (PGC) to be a predictor of disease risk." (PMID 39595853, 2024). "The second region, chr11:112755447-113889019, includes several genes among which is DRD2, which has been shown to be associated to numerous SUD traits and to schizophrenia, among other psychiatric traits." (PMID 38580809, 2024). "The objective of this study was to explore the correlation between DRD2, HTR2A, SLC6A4, CYP1A2, and ABCB1 polymorphisms and clozapine response in 100 patients with Treatment-Resistant Schizophrenia." (PMID 38540209, 2024). "Piperacetazine was discovered in the 1960s and approved by the FDA for the treatment of schizophrenia as a phenothiazine derivative that acts via dopamine D2 receptor (DRD2) antagonism." (PMID 37732905, 2023). "This study aimed to investigate the association between four polymorphisms in DRD2, DRD4 and COMT genes and their gene-gene interactions with antipsychotic treatment response in patients with schizophrenia." (PMID 37880658, 2023). "Amisulpride is a DRD2/DRD3/HTR7 inhibitor that has been widely used in high doses to treat schizophrenia and in low doses for the treatment of depressive disorders." (PMID 37014697, 2023). "Taking the downregulation of DRD2 as an indicator for increased mesolimbic dopaminergic neurotransmission, it can be assumed that the rat model mimics the situation in schizophrenia quite well." (PMID 36481661, 2022).